Y_RNA (Y RNA )
Gene: Miscellaneous RNA gene on chromosome 20 (45,004,348 to 45,004,454, forward strand). Ensembl gene ENSG00000252021.
Homologues: Paralogues in human: Y_RNA (56% identical), Y_RNA (55% identical), Y_RNA (54% identical), Y_RNA (53% identical), Y_RNA (52% identical), Y_RNA (51% identical), RNY3P8 (50% identical), Y_RNA (50% identical), Y_RNA (49% identical), Y_RNA (47% identical), Y_RNA (46% identical), RNY3P5 (45% identical), and 79 more.